FGF5 (fibroblast growth factor 5)
Description:
Plays an important role in the regulation of cell proliferation and cell differentiation. Required for normal regulation of the hair growth cycle. Functions as an inhibitor of hair elongation by promoting progression from anagen, the growth phase of the hair follicle, into catagen the apoptosis-induced regression phase (By similarity).
Synonyms: HBGF-5; Smag-82; TCMGLY
Tractability: Antibody: UniProt places it where antibodies can reach, with high confidence; its Gene Ontology location is reachable by antibodies, with high confidence; UniProt predicts a signal peptide or a membrane-spanning region.
Gene: Protein-coding gene on chromosome 4 (80,266,639 to 80,336,680, forward strand). Ensembl gene ENSG00000138675.
Subcellular location: Secreted
Pathways (Reactome):
Signal Transduction: Downstream signaling of activated FGFR1; FGFR1c ligand binding and activation; FGFR2c ligand binding and activation; FGFR3c ligand binding and activation; FGFRL1 modulation of FGFR1 signaling; FRS-mediated FGFR1 signaling; FRS-mediated FGFR2 signaling; FRS-mediated FGFR3 signaling; Negative regulation of FGFR1 signaling; Negative regulation of FGFR2 signaling; Negative regulation of FGFR3 signaling; PI-3K cascade:FGFR1; PI-3K cascade:FGFR2; PI-3K cascade:FGFR3; PI3K Cascade; PI5P, PP2A and IER3 Regulate PI3K/AKT Signaling; PIP3 activates AKT signaling; Phospholipase C-mediated cascade: FGFR1; Phospholipase C-mediated cascade; FGFR2; Phospholipase C-mediated cascade; FGFR3; RAF/MAP kinase cascade; SHC-mediated cascade:FGFR1; SHC-mediated cascade:FGFR2; SHC-mediated cascade:FGFR3
Disease: Activated point mutants of FGFR2; Constitutive Signaling by Aberrant PI3K in Cancer; Signaling by FGFR1 in disease; Signaling by FGFR2 in disease; Signaling by FGFR3 in disease; Signaling by activated point mutants of FGFR1; Signaling by activated point mutants of FGFR3
Gene Ontology:
Molecular function: fibroblast growth factor receptor binding; growth factor activity
Biological process: fibroblast growth factor receptor signaling pathway; positive regulation of cell population proliferation; cell-cell signaling; nervous system development; neurogenesis; positive regulation of MAPK cascade; regulation of cell migration; signal transduction
Cellular component: cytoplasm; extracellular region
Genetic constraint (gnomAD): Loss-of-function variants: 16 observed, 17.13 expected, observed/expected ratio (o/e) 0.93, 90% interval 0.63 to 1.42. The upper end of that interval is the gene's LOEUF score, 1.42, which puts it in group 5 of 6, group 1 being the genes least tolerant of losing a copy. Missense variants: 309 observed, 308.31 expected, observed/expected ratio (o/e) 1, 90% interval 0.91 to 1.1. Synonymous variants: 142 observed, 116.19 expected, observed/expected ratio (o/e) 1.22, 90% interval 1.07 to 1.4.
Homologues: Orthologues: chimpanzee FGF5 (99% identical), macaque FGF5 (98% identical), rabbit FGF5 (91% identical), pig FGF5 (89% identical), guinea pig FGF5 (87% identical), dog FGF5 (87% identical), mouse Fgf5 (84% identical), rat Fgf5 (84% identical), tropical clawed frog fgf5 (63% identical), zebrafish fgf5 (52% identical). Paralogues in human: FGF3 (29% identical), FGF6 (28% identical), FGF4 (28% identical), FGF20 (27% identical), FGF9 (26% identical), FGF16 (25% identical), FGF10 (25% identical), FGF7 (24% identical), FGF2 (22% identical), FGF11 (22% identical), FGF13 (22% identical), FGF22 (21% identical), and 9 more.
Diseases named in the same sentence as FGF5 in open-access papers:
FGF5 is named in the same sentence as 99 diseases in open-access papers, as found by Europe PMC text mining. Sharing a sentence is not in itself a finding about the gene and the disease. The quoted sentences say what the papers report.
Hypertension (21 papers, 2016 to 2026). The presence of chronic increased pressure in the systemic arterial system. "FGF5 has been implicated in GWAS of hypertension, and other fibroblast growth factors are increasingly recognised as contributors to blood pressure regulation through renal mechanisms." (PMID 40538118, 2025). "In humans, variants in the FGF5 gene are associated with blood pressure regulation and an increased risk of hypertension." (PMID 40869975, 2025). "For the hypertension and atrial fibrillation pairing, signals implicating shared causal variants were seen on chromosomes 4, 7, 11, and 17, in the genes FGF5, HOXA13, in the region spanning LSP1 to TNNT3 and that spanning CYTH1 to USP36 respectively." (PMID 40538118, 2025). "A cis-pQTL for FGF5 was also associated with susceptibility to hypertension and cardiovascular diseases, with the allele associated with higher plasma FGF5 levels being associated with lower risk of cardiovascular diseases." (PMID 37563310, 2023). "This study has shown that poor blood pressure response to CCBs among Filipinos with hypertension appears to be associated with the variant rs1458038 near FGF5." (PMID 35119014, 2022). "For example, several hypertension-related variants, including rs1458038 in FGF5, rs1918975 in MECOM, and rs10774624 in SH2B3, were found to be significantly associated with the risk of preeclampsia." (PMID 36553520, 2022). "The SNPs we report near PRDM8/FGF5 on chromosome 4 showed pleiotropic risk associations with essential hypertension and severe depressive episode with psychotic symptoms." (PMID 35701404, 2022). "This study confirmed that FGF5 rs16998073 variants do place their carriers (men and women) at increased risk for developing hypertension." (PMID 32709000, 2020). "Carriers with at least one minor T allele for FGF5 rs16998073 were shown to be at significantly higher risk for developing hypertension." (PMID 32709000, 2020). "The most important finding of our study is the synergistic effect of FGF5 rs16998073 variants and sodium intake on the risk of hypertension in both men and women." (PMID 32709000, 2020). "The association between FGF5 rs16998073 and hypertension was also recapitulated in a study of East Asians, and this polymorphism was shown to be associated with salt sensitivity in Koreans." (PMID 32854392, 2020). "In this cross-sectional study, we identified an interaction between FGF5 rs16998073 variants and sodium/potassium intake, the sodium–potassium ratio, and increased risk for hypertension." (PMID 32709000, 2020). "GWAS analysis revealed that the FGF5 rs16698073 variant demonstrated the strongest association with hypertension in this population." (PMID 32709000, 2020). "This study aimed to examine the interaction between dietary sodium/potassium intake, sodium–potassium ratios, and FGF5 rs16998073 and link these with increased risk for developing hypertension." (PMID 32709000, 2020). "Despite these limitations, we believe that this study is the first to evaluate the interaction between FGF5 rs16998073, sodium and potassium intake, and the risk of hypertension in the Korean population." (PMID 32709000, 2020). "Multivariable logistic regression was used to examine the relationship between dietary intake of sodium, potassium, and sodium–potassium ratios and the FGF5 rs16998073 genotypes (AA, AT, TT) and any increased risk of hypertension." (PMID 32709000, 2020). "In the current study, FGF5 rs16998073 and PRDM8-FGF5 rs12509595 were significantly associated with an increased risk of hypertension both in participants with sodium intake < 2 g/day and in those with intake ≥2 g/day." (PMID 32854392, 2020). "Additional studies are needed to evaluate the effect of the FGF5 rs16998073 variants and their relationship with various dietary factors on the development of hypertension." (PMID 32709000, 2020).
Hypertension (continued). "FGF5 gene variance is reportedly associated with hypertension in humans, whereas a role of this gene in lipid/cholesterol metabolism has not been reported." (PMID 27708340, 2016). "In addition, it was shown that circulating FGF5 levels were associated with chronic inflammatory diseases, such as hypertension, spinal cord injury, malignances, and hepatic fibrosis." (PMID 38988665, 2024). "Notably, according to the genome-wide association studies, FGF5 polymorphism is significantly associated with hypertension susceptibility, and high levels of cortisol are the main causes of hypercortisolism." (PMID 38891117, 2024). "FGF5 was identified as a hypertension-associated gene that influences PE in Central Asian women." (PMID 36553520, 2022). "increase in genetically predicted FGF-5 levels was associated with a 12% higher risk of coronary artery disease (odds ratio: 1.12; 95% CI: 1.08–1.16; p value < 9.0 × 10−12) possibly via its effect on hypertension (1.32; 1.29–1.35; p value < 1.7 × 10−99)." (PMID 34819519, 2021). "However, only the FGF5 rs16998073 wild-type AA allele in women with a potassium intake ≥3500 mg per day demonstrated any protective effect for potassium in hypertension." (PMID 32709000, 2020). "Finally, we performed a logistic regression analysis to confirm the interaction between FGF5 rs16998073 genotypes, sodium and potassium intake, and the risk of hypertension." (PMID 32709000, 2020). "Therefore, our results do not provide any significant insight into the effects of potassium intake on FGF5 rs16998073 variants and their risk of hypertension." (PMID 32709000, 2020). "As shown by our results, the genetic effect of FGF5 rs1698073 might constitute a greater predisposition to hypertension over sodium/potassium intake." (PMID 32709000, 2020). "A study of Chinese children showed that interactions between a genetic risk score including ATP2B1 rs17249754, fibroblast growth factor 5 (FGF5) rs16998073 polymorphisms, and physical activity play important roles in the regulation of BP and the development of hypertension." (PMID 30857519, 2019). "FGF-5 rs16998073 polymorphisms were significantly associated with hypertension risk in East Asians." (PMID 30857519, 2019). "However, a number of other studies focused on identifying causative genes for hypertension have identified the genetic expression of C4orf22 (chromosome 4 open reading frame 22), which is near FGF5 and other genes, as a causative gene for hypertension rather than FGF5 itself." (PMID 32709000, 2020). "It is of interest that FGF5 lies within a colocalisation locus for not only hypertension and atrial fibrillation, but also for CKD." (PMID 40538118, 2025). "The cis-pQTL SNP used as genetic instrument for FGF5 has been linked to CHD16 and to blood pressure in previous studies.Thus, FGF5 is probably a protein of interest for several CVDs, since hypertension is causally related to all major CVDs23." (PMID 39322770, 2024). "Recent studies have indicated that FGF5 also plays a significant role in cardiovascular conditions such as hypertension and coronary artery disease (CAD)." (PMID 39563941, 2024). "Among the hypertension results, the most significant association was found in the HTN-L5:FGF5 gene region, and the trends were consistent in all study groups." (PMID 36233190, 2022). "Examples of genetically anchored protein–disease connections included: TNFSF11 (RANKL) with osteoporosis and hypothyroidism, NGF (nerve growth factor) with migraine, TNFSF12 (TWEAK) with hypertension and fibroblast growth factor 5 (FGF5) with hypertension and cardiovascular diseases." (PMID 37563310, 2023). "In this study, a GWAS using TWB data to test the association of SNPs with hypertension reported 6 SNPs (rs1458038 in FGF5, rs3796605 in FGF5, rs455938 in MAST4, rs10866754 in CTC-535M15.2, rs648435 in APHGAP42, and rs2018159 in APHGAP42) to be significantly associated (P < 5e-6) with hypertension." (PMID 34901208, 2021).
Hypertension (continued). "A recent study showed an abnormal expression of FGF5 mRNAs and proteins in hypertensive populations, suggesting that FGF5 may be involved in the development of hypertension." (PMID 32709000, 2020). "Our results indicate that the minor T allele of FGF5 rs16998073 is an indicator of increased risk for hypertension regardless of gender, sodium/potassium intake, and sodium–potassium ratios." (PMID 32709000, 2020). "In addition, we identified three SNPs in two novel genes (LOC729251 and TCEANC) and seven SNPs in five previously reported genes (FGF5, ATP2B1, CYP17A1, MTHFR and CASZ1) nominally associated with hypertension (Pmeta < 0.05)." (PMID 27480026, 2016). "Notably, four loci (rs11899121 [chr2p24], rs7556898 [chr2q24.3], rs17249754 [ATP2B1], and rs1980854 [chr20p12.2]) were significantly associated with hypertension in the high-METS-IR group (T3), rs10857147 (FGF5) was significant in both T1 and T3, and rs671 (ALDH2) was significant only in T1." (PMID 39684400, 2024). "In addition, a Bayesian-network-based predictive model for hypertension suggests that FGF5 rs16998073 could be a deciding factor in the development of hypertension." (PMID 32709000, 2020). "Lastly, the rs10857147 marker in the FGF5 gene increased the prevalence of hypertension irrespective of METS-IR levels." (PMID 39684400, 2024). "Another study showed that FGF5 and ZNF652 might be related to each other and affected each other’s transcriptional activity, thereby altering the prevalence of hypertension in the Chinese Han population." (PMID 32709000, 2020).
breast carcinoma (14 papers, 2011 to 2023). "These contrasting results need further studies to uncover the mechanisms underlying FGF5 signalling in breast cancer." (PMID 35193394, 2022). "Increased expression of FGF5 was associated with pancreatic cancer, and high FGF5 expression was found in cell lines from renal cell carcinoma (6 of 10) prostate cancer (2 of 3) and breast cancer (1 of 2)." (PMID 29152117, 2017). "Then, FGFR2 activated HER2 through c-Src, leading to resistance of HER2 targeted therapies, considering the TAF/FGF5/FGFR2/c-Src/HER2 axis was the escape pathway of HER2 targeted therapy resistance in breast cancer." (PMID 37174034, 2023). "TAF produce and secrete high fibroblast growth factor 5 (FGF5) to activate fibroblast growth factor receptor 2 (FGFR2) in surrounding breast cancer cells." (PMID 37174034, 2023). "FGF4 signalling regulates breast cancer cell migration and invasion, whereas FGF5 seems to have a specific role in the formation of bone metastasis as shown by its overexpression in metastatic samples compared with normal breast." (PMID 35193394, 2022). "Fibroblast growth factor 5 (FGF5) was reported to induce resistance to HER2-targeted therapies in breast cancer." (PMID 35812404, 2022). "In the context of breast cancer, the expression of FGF5 and FGF6 was detected at very low level in comparison with FGF1 and FGF2." (PMID 35193394, 2022). "In addition, studies have demonstrated that FGF5 levels in the stroma can be a method for predicting efficacy of trastuzumab in treating HER2-positive breast cancer patients." (PMID 36276152, 2022). "However, it has also been reported that low expression of FGF5 correlates with a protective role in breast cancer patients." (PMID 35193394, 2022). "We recognize that breast cancer cells may produce secreted factors other than FGF-5 that induce expression of CCL5." (PMID 33868996, 2021). "FGF4 promotes resistance to lapatinib in HER2-positive breast cancer cell lines through FGFR1 signalling, and FGF5 by inducing FGFR2 activation, which in turns transactivates HER2 and promotes resistance." (PMID 35193394, 2022). "Furthermore, the authors showed that FGF5 secreted by cancer-associated fibroblasts (CAF) in the microenvironment might be responsible for the high activation of FGFR2 on the neighboring epithelial cells, confirming the potential signaling switch between HER2 and FGFR2 in breast cancer." (PMID 38139837, 2023). "Furthermore, the authors showed that FGF5 secreted by cancer-associated fibroblasts (CAF) in the microenvironment might be responsible for the high activation of FGFR2 on the neighbouring epithelial cells, confirming the potential signalling switch between HER2 and FGFR2 in breast cancer." (PMID 35193394, 2022).
melanoma (11 papers, 2017 to 2025). A malignant, usually aggressive tumor composed of atypical, neoplastic melanocytes. "FGF5 overexpression in melanoma cells suggests pro-tumorigenic functions with enhanced malignancy through paracrine effects." (PMID 39796775, 2025). "FGF5 has been shown to affect proliferation and migration in melanoma and glioblastoma multiforme models while GNAQ activates PKC, FAK, and ERK signaling cascades to promote proliferation and cell survival in uveal melanoma." (PMID 37016431, 2023). "FGF5 can promote osteosarcoma proliferation by activating the MAPK signaling pathway and the FGF5/FGFR1 axis contributes to melanoma progression." (PMID 33935975, 2021). "FGF5 protein has been recently shown to be endogenously overexpressed in a subset of melanoma cell lines and in more than 60% of benign nevi and melanoma specimens." (PMID 31167513, 2019). "For instance, FGF2 transcript levels were more than 100-fold higher in half of melanoma cell lines than in normal melanocytes, and FGF5 in 1/3 of melanoma cell lines." (PMID 31167513, 2019). "To select appropriate cell models, we initially screened normal human melanocytes and a panel of 28 human melanoma cell lines for FGF5 gene expression by qPCR." (PMID 29152117, 2017). "Immunohistochemistry performed on a tissue microarray demonstrated FGF5 protein expression in more than 50% of samples of melanoma and benign nevi." (PMID 29152117, 2017). "In 12 of 28 melanoma cell lines in contrast, FGF5 was highly expressed (> 50-fold compared to normal melanocytes)." (PMID 29152117, 2017). "This highlights the importance of further evaluating FGF5 as potential biomarker and therapy target in melanoma." (PMID 29152117, 2017). "Data downloaded from the Cancer Genome Atlas (TCGA) further support FGF5 expression in tumor tissue from subsets of human melanoma patients." (PMID 29152117, 2017). "In an in vivo experiment in immunocompromised mice, human melanoma xenografts overexpressing FGF5 showed enhanced tumor growth, a higher Ki-67 proliferation index, decreased apoptosis and enhanced angiogenesis." (PMID 29152117, 2017). "In summary, we show for the first time the expression of FGF5 protein in a substantial fraction of nevus and melanoma tissues and provide evidence for pro-tumorigenic functions of FGF5 in melanoma." (PMID 29152117, 2017). "FGFR1, the predominant receptor for FGF5, is abundantly expressed in melanoma cells and likely is responsible for transducing autocrine stimulation by FGF5." (PMID 29152117, 2017). "To analyze a potential contribution of FGF5 to malignant growth of melanoma cells, we ectopically expressed human FGF5 in two cell lines, VM1 and VM21, with low endogenous FGF5 levels." (PMID 29152117, 2017). "Positive FGF5 immunoreactivity was detected in 14 of 23 benign nevi (61%) 36 of 56 primary melanomas (77%) and 13 of 20 metastatic melanomas (75%)." (PMID 29152117, 2017). "With respect to melanoma, we and other groups have previously observed FGF5 expression in some melanoma cell lines in contrast to normal melanocytes, where FGF5 is hardly detectable." (PMID 29152117, 2017). "Silencing of FGF5 in melanoma cells with high endogenous FGF5 expression had the opposite effect on clonogenicity." (PMID 29152117, 2017). "Overexpression of FGF5 may promote melanoma growth through increased activation of the MAPK pathway." (PMID 39796775, 2025). "Some of the genes involved in both ‘Pathways in cancer’ and ‘Melanoma’ are Fgf2, Fgf5, and Pdgfa." (PMID 36009225, 2022). "In the reverse approach, we tested whether knock-down of FGF5 in melanoma cells with high endogenous FGF5 expression would reduce their growth capacity." (PMID 29152117, 2017). "In the current study, we demonstrate that FGF5 expression contributes to the malignancy of melanoma cells in vitro as well as in a mouse xenotransplant model and show that FGF5 protein is expressed in a considerable fraction of human melanoma tissue samples." (PMID 29152117, 2017).